TNF (tumor necrosis factor)
Diseases named in the same sentence as TNF in open-access papers (continued):
Sharing a sentence is not in itself a finding about the gene and the disease.
Crohn disease (continued). "Using large cohorts of 225,090 and 188,420 patients with Crohn’s disease or ulcerative colitis, respectively, it was demonstrated that those treated with anti-TNFα agents were less likely to develop colorectal cancer." (PMID 33540543, 2021). "Previous research has also found that rs976881 T/T is less responsive than T/C to anti-TNFα maintenance therapy (infliximab) in patients with Crohn's disease." (PMID 33716716, 2021). "In macrophages, SCFAs inhibit NFκB activation in the presence of TNF (implications for Crohn's disease, 2000)." (PMID 33463911, 2021). "In children with Crohn’s disease, anti-TNF therapy lowers inflammatory cytokines TNF and IL-6 and increases plasma calcitriol and PTH, but not iFGF23 levels." (PMID 33416083, 2021). "The current treatment of choice for polyarthralgia in Crohn's disease consists of disease-modifying agents and anti-inflammatory therapy, such as anti-tumor-necrosis-factor alpha inhibitors like infliximab." (PMID 34327073, 2021). "We describe the case of a 67-year-old female with severe Crohn's disease receiving anti-tumor necrosis factor-alpha (TNF-α) therapy, Etanercept presenting with localized Escherichia coli (E." (PMID 33859909, 2021). "Anti-TNFα and anti-IL-23 antibodies are highly effective therapies for Crohn’s disease or ulcerative colitis in a proportion of patients." (PMID 34593832, 2021). "The chimeric antibody infliximab neutralizes TNF-α and is effective in Crohn’s disease and rheumatoid arthritis." (PMID 32444946, 2021). "Previous studies showed that the abundance of Erysipelotrichaceae was significantly increased in C57BL/6J mice infected with Toxoplasma gondii or Giardia muris or TNF-divern Crohn’s disease (CD)-like transmural inflammation." (PMID 34945541, 2021). "Our aim was to study the immunological profile and clinical evolution of patients with Crohn’s disease according to the anti-TNF dose and serum trough levels." (PMID 35046819, 2021). "Like AZA, the anti-TNF-α antibody can restore intestinal microbial diversity in patients with Crohn’s disease by decreasing Proteobacteria but increasing Bacteroidetes." (PMID 35004341, 2021). "Thalidomide inhibits production of TNF-α and other inflammatory mediators and is clinically used in Crohn’s disease, despite unclear mechanism of action." (PMID 32444946, 2021). "TNFRSF1A:rs767455 (36T/C) was found to have an impact on anti-TNF-alpha clinical outcomes among patients with Crohn’s disease." (PMID 33807923, 2021). "Data on the effectiveness of anti-tumor necrosis factor medications in patients with Crohn’s disease (CD) with poor prognostic factors (PPFs) are scarce." (PMID 36777275, 2021). "Here, we report the case of a 23-year-old patient with ileocolonic Crohn’s disease in endoscopic remission under ongoing anti-TNF infliximab therapy with occurrence of novel generalized arthralgia, pleuritic chest pain, and dyspnea." (PMID 34616488, 2021). "In this study, fresh blood and serum samples were used to identify biomarkers and to discriminate between Crohn’s disease and ulcerative colitis patients under remission treated with anti-TNF." (PMID 34021361, 2021). "ED suppressed the levels of mucosal inflammatory cytokines, specifically reducing the production of cytokines like TNF-α and IL-6 in the mucosa in patients with Crohn’s disease." (PMID 34626918, 2021). "In particular, LPS activates pathways that are directly involved in the progression of Crohn’s disease and ulcerative colitis, particularly the NF-κB pathway, which increases levels of IL-1, IL-6, and TNF-α, among others." (PMID 34200555, 2021). "The samples were obtained from the patients with anti-TNF therapy for over 3 months and the Simple Endoscopic Score for Crohn’s disease (SES-CD) <5." (PMID 33986682, 2021). "Anti-TNF agents have been shown to improve psychological well-being in patients with psoriasis, cancer and Crohn’s disease." (PMID 33498197, 2021).
Crohn disease (continued). "Here we report the potential roles of hsa_circRNA_103765 in regulating cell apoptosis induced by TNF-α in Crohn’s disease (CD)." (PMID 33436852, 2021). "TNF-α inhibitors also significantly reduce CRP levels in patients who have either metabolic syndrome or Crohn’s disease." (PMID 34829740, 2021). "Studies have also demonstrated that the minor allele of rs1061622 is also related to sTNFR2 levels and response to anti-TNFα maintenance therapy in patients with Crohn's disease." (PMID 33716716, 2021). "TNFα inhibitors are used for treatment of many systemic (e.g., Crohn's disease) and neurologic (e.g., neurosarcoidosis, Behcet disease) chronic inflammatory disorders." (PMID 34305787, 2021). "In this regard, while 35% of Crohn’s disease patients underwent anti-TNF therapy, 24% of ulcerative colitis patients received these agents (p = 0.13)." (PMID 34575213, 2021). "The pretreatment TREM-1 expression levels of CD14+ monocytes of Crohn’s disease (CD) patients were predictive of outcome to anti-TNF mAb therapy, with low TREM-1 expression associated with response to anti-TNF." (PMID 33790898, 2021). "The abundance of Bacteroides (Bacteroidetes) and Faecalibacterium (Firmicutes) was greater in TNF-α refractory patients suffering from Crohn’s disease, who achieved remission following ustekinumab therapy." (PMID 33926088, 2021). "Lachnospiraceae and Ruminococcaceae families, typically producing SCFAs, define the frequently relapsing disease and poor treatment response to anti-TNF-α in Crohn’s disease." (PMID 35004341, 2021). "Infliximab, an anti-TNF monoclonal antibody, has been an adequate therapy for Crohn’s disease worldwide, and its effect is based on neutralizing the bioactive TNF in the intestinal mucosa, as well as it can promote apoptotic T-cell death." (PMID 34834950, 2021). "We report a 14-year-old man with Crohn's disease (CD) who developed right upper arm pain while being treated with the anti-tumor necrosis factor (TNF)-alpha monoclonal antibody, infliximab." (PMID 34685390, 2021). "We report a rare case of isolated pulmonary cryptococcosis in a patient undergoing anti-TNF-α therapy for Crohn's disease." (PMID 34401295, 2021). "In patients with moderate to severe Crohn’s disease (CD) who had failed prior treatment with TNF-α blockade, another human IL-23-blocking Mab also showed clinical improvement in a Phase 2A study." (PMID 34992594, 2021). "Anti-TNF-α therapy in Crohn’s disease, a disorder characterized by overproduction of TNF-α resulted in higher levels of PTH." (PMID 33861790, 2021). "Taken together, those findings suggest a definite distinct role of TNF in the early vs. late phase of the inflammatory process leading to Crohn’s disease." (PMID 34638616, 2021). "We found that the salivary concentration of TNF-R1, one of the receptors for TNF-α, was significantly reduced in patients with ulcerative colitis relative to patients with Crohn’s disease and the controls." (PMID 34575091, 2021). "A study conducted in North America between the years 2004–2010 focused on outcomes resulting from an anti-TNF therapy in 6273 patients suffering from Crohn’s disease." (PMID 34903253, 2021). "A recent study researched the evolution of the subjects with Crohn’s disease with a good response to the anti-TNF α biological treatment and treatment-induced ultrasound changes." (PMID 34377195, 2021). "Data were stratified by medical condition (ulcerative colitis vs. Crohn’s disease), anti-TNF drug and follow-up." (PMID 34069295, 2021). "Selection: prospective and retrospective studies assessing DI in Crohn’s disease and ulcerative colitis patients treated for at least 12 weeks with an anti-TNF drug." (PMID 34069295, 2021). "In another study, genetic polymorphisms in TNF-alpha receptors illustrated a variable response to treatment with TNF-alpha inhibitors in patients with Crohn’s disease." (PMID 33807923, 2021).
Crohn disease (continued). "Anti-tumour necrosis factor alpha (TNFα) therapy is widely used in the management of Crohn’s disease (CD) and ulcerative colitis (UC)." (PMID 34534227, 2021). "This anti-TNF-alpha effect of the vagus nerve can be used in the treatment of chronic inflammatory bowel diseases, represented by Crohn’s disease and ulcerative colitis where this cytokine plays a key role." (PMID 33828455, 2021). "Anti-TNFα therapy has been approved to use in Crohn’s disease since 1998, including monoclonal antibodies or fragments thereof directed against TNF molecules, such as Infliximab (IFX), Adalimumab (ADA), Certolizumab pegol (Cimzia)." (PMID 34681815, 2021). "This polysaccharide is known to induce the production of tumor necrosis factor-α (TNF-α), which contributes to the inflammation observed in Crohn’s disease." (PMID 34503577, 2021). "The aim of this study was to compare the perianal fistula closure rates following treatment with anti-tumor necrosis factor (TNF) agents or autologous adipose tissue-derived stem cell (auto-ASC) transplantation with Crohn’s disease (CD)." (PMID 34256838, 2021). "Reduction of the elevated levels of TNF that promote intestinal inflammation in Crohn’s disease has been a therapeutic success." (PMID 35095387, 2021). "It is therefore likely that among minor allele (T/T) carriers with Crohn's disease, higher levels of TNFR2 counteract TNF-α, making infliximab less effective." (PMID 33716716, 2021). "There are several biological agents approved globally to treat both Crohn’s disease (CD) and ulcerative colitis (UC), with different mechanisms of action: tumor-necrosis factor (TNF) inhibitors, anti-integrins, and anti-interleukins." (PMID 34884344, 2021). "The authors proved that the expression of MACC1 in inflamed tissues from ulcerative colitis and Crohn’s disease patients is upregulated by TNFα through NF-κB signaling pathway, via TNFR1, which lead to an increase in cell migration." (PMID 33540543, 2021). "For instance, ILC1s can protect against infection from an intracellular parasite by producing IFN-γ and TNF, but ILC1s also accumulate in the inflamed intestines of people with Crohn's disease and produce the proinflammatory cytokine IFN-γ." (PMID 33688303, 2021). "Other biological immunomodulators, such as ustekinumab, an mAb against IL12/IL23, showed efficiency in moderately to severely active Crohn’s diseases, and brought clinical benefits in many patients who had failed anti-TNF treatment." (PMID 34059101, 2021). "Infliximab (IFX) was the first licensed anti-tumor necrosis factor (TNF) approved for pediatric use in 2006 for treating Crohn's disease (CD)." (PMID 34123968, 2021). "Similar results were seen on stratified analysis by disease phenotype (Crohn's disease and ulcerative colitis) and index biologic therapy (tumor necrosis factor-α antagonists and vedolizumab)." (PMID 34228004, 2021). "Among the eight IBD patients who developed ON, only one patient was diagnosed with Crohn’s disease, the male gender was slightly dominant, and two (25%) patients received antitumor necrosis factor α (anti-TNF α) treatment for IBD." (PMID 33578895, 2021). "Exclusion criteria: studies using anti-TNF as a prophylaxis for the postoperative recurrence in Crohn’s disease or those where DI was based on therapeutic drug monitoring." (PMID 34069295, 2021). "In fact, our findings were well correlated with the report about GSE111761 that in patients with Crohn’s disease receiving anti-TNF therapy, there were significant upregulations of mucosal Il-23p19, Il23R and Il17A in non-responders, but not in responders." (PMID 33193322, 2020). "Increased level of TNF-α was observed in the serum of patients with ulcerative colitis and Crohn's disease." (PMID 32149087, 2020). "Patients with active Crohn’s disease starting glucocorticoids or anti-tumor necrosis factor were included." (PMID 31651651, 2020).
Crohn disease (continued). "Biologicals like anti-tumor necrosis factor (TNF) therapy for Crohn’s disease (CD) are safe and effective but there is a significant rate of primary and secondary nonresponse in the patients." (PMID 32612148, 2020). "The management of Crohn’s disease (CD) has been profoundly modified by theintroduction of biological treatments, in particular by the availability of tumornecrosis factor-a (TNF-a) inhibitors." (PMID 33237166, 2020). "Infliximab is a mAb which works as anti-TNF-α and it is currently approved for treatment of Crohn’s disease (CD) and in ulcerative colitis (UC) in children from 6 years of age." (PMID 32408641, 2020). "Certolizumab is a subcutaneously administered selective immunosuppressive and anti-inflammatory TNF-α-inhibitor used to treat rheumatoid and psoriatic arthritis, spondyloarthritis, and Crohn’s disease." (PMID 32421085, 2020). "In this prospective observational study, we evaluated the criterion validity and responsiveness of the BSFS and VAS as outcome measures for Crohn’s disease in patients starting with corticosteroids or TNF inhibitors for active disease." (PMID 31651651, 2020). "Infliximab is an intravenously administered selective immunosuppressive and anti-inflammatory TNF‐α inhibitor used to treat rheumatoid and psoriatic arthritis, Crohn’s disease, and ankylosing spondylitis." (PMID 32421085, 2020). "To test his, we used Infliximab, a TNF-α inhibitor in clinical use against ulcerative colitis and Crohn’s disease." (PMID 33267818, 2020). "In this retrospective chart review, 7 out of 10 patients with anti-TNF refractory pediatric-onset Crohn’s disease required augmented maintenance doses of ustekinumab to achieve clinical response or remission as measured by abbrPCDAI." (PMID 34504690, 2020). "Cimzia is the only anti-TNF-α antibody which is especially administered for patients suffering from Crohn’s disease." (PMID 33116155, 2020). "In patients with moderate to severe Crohn's disease naive to anti-TNF treatment, Adalimumab induced and maintained clinical remission for up to 56 weeks." (PMID 33415035, 2020). "Strength of this study is the prospective collection of data in a real-life cohort of patients with Crohn’s disease who require TNF inhibitors or corticosteroids for active disease." (PMID 31651651, 2020). "Most of the Crohn’s disease sample was taking medication to control their disease, and 3 in 4 were receiving an anti-Tumor Necrosis Factor inhibitor, which is given to individuals with moderate to severe illness to initiate and maintain remission." (PMID 32052205, 2020). "Glucocorticoids (GCs; e.g., the synthetic dexamethasone (Dex)), which function by binding to the glucocorticoid receptor (GR), confer protection against Crohn's diseases and against TNF‐induced intestinal damage and lethal shock, when given prior to TNF." (PMID 32914580, 2020). "Crohn’s disease medications used within the 2 years before vedolizumab or anti-TNFα index treatment initiation, respectively, included corticosteroids (58% vs 63%), aminosalicylates (29% vs 40%), and immunomodulatory agents (28% vs 53%)." (PMID 32640990, 2020). "The antagonist to TNF-α has been approved for the management of Crohn's disease and its complications." (PMID 33415035, 2020). "Another experiment demonstrated that Lactobacillus casei and Lactobacillus bulgaricus significantly reduced the TNF-α production in the mucosa of Crohn's disease patients." (PMID 32104535, 2020). "For example, patients with rheumatoid arthritis, spondylarthritis, and Crohn’s disease, and treated with anti-TNF-α agents, have benefited from concomitant methotrexate treatment." (PMID 32408641, 2020). "PIMS analysis was performed in peripheral blood taken prior to the first vedolizumab application in 20 IBD patients (Crohn disease n = 13; ulcerative colitis n = 7) refractory to at least 1 previous anti-TNF agent therapy." (PMID 32776006, 2020).
Crohn disease (continued). "Adalimumab is a clinically approved TNF-α neutralizing monoclonal antibody applied widely in the treatment of chronic inflammatory diseases including Crohn's disease and ulcerative colitis." (PMID 32670264, 2020). "Patients with ulcerative colitis have higher baseline levels of IL1β and TNF-α than in patients with Crohn’s disease." (PMID 32933548, 2020). "This study investigated the effect of azathioprine/6-mercaptopurine (6-MP) and TNF-α antagonists on abdominal and perianal surgery in Korean patients with Crohn’s disease." (PMID 33374886, 2020). "For instance, TNF-α inhibitors, except for etanercept, are considered first-line therapies for moderate to severe Crohn’s disease." (PMID 32512854, 2020). "We have previously observed a more favorable clinical outcome in those patients treated with TNFα inhibitors for Crohn disease who experienced a paradoxical increase in soluble TNFα during therapy." (PMID 30675683, 2019). "Infliximab and adalimumab, both anti-TNFα monoclonal antibodies, are currently used for treating Crohn’s disease." (PMID 31238939, 2019). "Increased production of IL-1β and TNFα in inflamed Crohn's disease mucosa induces the synthesis of IL-8, which is an effective neutrophil chemoattractant." (PMID 31191826, 2019). "The first FDA approved anti-TNF for Crohn's disease was Infliximab (IFX) introduced in 1998, the second was Adalimumab (ADA) in 2007 and, more recently, Golimumab and Certolizumab became available." (PMID 31737635, 2019). "In another study in Crohn's Disease, AnxA1 is involved in intestinal homeostasis after anti-TNF-α treatment and suggested as a potential biomarker of therapeutic efficacy of anti-TNF-α treatment." (PMID 31396220, 2019). "Implantable bioelectronic devices targeting the inflammatory reflex reduce TNF production and inflammation in preclinical models of inflammatory disease, and in patients with RA and Crohn’s disease." (PMID 32232095, 2019). "This is a valid preclinical model, that has been widely used for the development of approved drugs, which are effective in the therapy of Crohn’s disease and ulcerative colitis, such as anti-TNF-α and anti-α4β7-integrin antibodies and probiotics for example." (PMID 31276514, 2019). "IL-1β and TNFα expression in patients with Crohn’s disease has been shown to lead to increased intestinal permeability." (PMID 30755679, 2019). "In fact, TNF‐α production by intestinal epithelial cells has been shown to be key in initiating pathology in Crohn's disease (Roulis, Armaka, Manoloukos, Apostolaki, & Kollias, 2011)." (PMID 31199577, 2019). "For example, TNF-α, which is critical to Crohn’s disease pathogenesis, impairs gut barrier integrity via MLC phosphorylation and occludin internalization." (PMID 31182728, 2019). "In another small-scale study, increased inflammation was found in 43 subjects with active Crohn’s disease (CD), as indicated by high levels of plasma TNF-α and CRP, compared with healthy controls." (PMID 31213029, 2019). "Although Crohn's disease patients with wtIL26 or varIL26 genotypes exhibit similar rates of circulating bacterial DNA, the concentrations of IFNγ, IL-12, and TNFα are elevated in patients with a varIL26 genotype and containing circulating bacteria DNA." (PMID 30809226, 2019). "In Crohn's disease, AnxA1 biosynthesis is dysregulated and higher levels correlate with successful intervention with biologicals against TNF-α." (PMID 31396220, 2019). "The production of TNFα is also high in cultured mucosal mononuclear cells from Crohn's disease patients." (PMID 31191826, 2019). "In Crohn’s disease, we reported that SNPs in TNFα and receptors (TNFRSF1A/TNFRSF1B) benefited intracellular MAP-survival, increased infection, and elevated inflammatory response mimicking the poor response to anti-TNFα treatment in some patients." (PMID 31817071, 2019).